WT1 (WT1 transcription factor)
Diseases named in the same sentence as WT1 in open-access papers (continued):
Sharing a sentence is not in itself a finding about the gene and the disease.
chronic myeloid leukemia (28 papers, 2007 to 2025). "Additionally, overexpression of WT1 mRNA is also found in chronic myelocytic leukaemia (CML) and myelodysplastic syndrome, and is associated with disease progression." (PMID 37296375, 2023). "The aberrant expression or mutation of WT1 has been reported in conditions such as MDS and chronic myeloid leukemia (CML), often correlating with poor prognosis and therapy resistance." (PMID 40507300, 2025). "We exposed in vitro CD8+ transgenic WT1-specific T cells targeting the HLA A*0201-restricted WT137-45 epitope (TTCR37-45) to high-WT1-expressing HLA-A*0201-transduced K562 acutely transformed chronic myelogenous leukemia." (PMID 40473616, 2025). "The WT1 gene is usually used for monitoring the progression of BCR-ABL positive chronic myeloid leukemia." (PMID 36078884, 2022). "Conversely, WT1 is frequently overexpressed in AML, MDS, and blast crisis of chronic myeloid leukemia, and expression levels are associated with increased blast counts, higher risk of progression and relapse, resistance to therapy, and poor OS." (PMID 33917307, 2021). "WT1 plays an oncogenic role in a wide range of solid tumors and hematopoietic malignancies, including chronic myelogenous leukemia (CML)." (PMID 26320177, 2015). "Wilms’ tumor 1 (WT1) gene, an oncogene that has been shown to be overexpressed in the wild-type form in the blast and crisis phase of chronic myelogenous leukemia and also acute lymphoblastic and myeloblastic leukemia, binds to the promoter region of BAG3 and acts as a transcriptional activator." (PMID 36980278, 2023). "Interestingly, ZNF224 expression was lower in chronic granulocytic leukemia and exhibited proapoptotic and antiproliferative effects with the ancillary transcription factor WT1." (PMID 36085146, 2022). "In addition, prognostic value WT1 expression was demonstrated in CML (chronic myelogenous leukemia), in which a high level of WT1 expression is detected in CML patients with relapse while remaining low in the patients with complete remission." (PMID 33110919, 2020). "High levels of WT1 expression were originally found to be associated with poor prognosis in adult AML patients and used as a marker for the detection of minimal residual disease in AML, as well as in acute lymphoblastic (ALL) and chronic myeloid leukaemia (CML)." (PMID 26597595, 2016). "Specifically, in a chronic myelogenous leukemia cell line, ZNF224 was shown to augment the signaling of Wilms’ Tumor 1 (WT1), which is a known TSG that controls the expression of genes involved in differentiation, apoptosis, and cell cycle progression." (PMID 30444046, 2019). "WT1 mRNA is overexpressed in various solid cancers, as well as hematologic malignancies, including AML, acute lymphocytic leukemia (ALL), chronic myeloid leukemia (CML), and MDS." (PMID 29662637, 2018). "The transcription factor ZNF224 plays a key proapoptotic role in chronic myelogenous leukemia (CML), by modulating Wilms Tumor protein 1 (WT1) dependent apoptotic genes transcription." (PMID 29423056, 2018). "Similar to AML, chronic myeloid leukemia cases with BCR-ABL translocations had unmethylated WT1 promoters and AWT1 hypermethylation, however, polycythaemia vera and essential thrombocythaemia samples had methylation profiles indistinguishable from normal leukocyte controls." (PMID 24405639, 2014).
glioma (28 papers, 2009 to 2024). A benign or malignant brain and spinal cord tumor that arises from glial cells (astrocytes, oligodendrocytes, ependymal cells). "Recently, there have been trials to associate WT1 expression with several prognostic indicators in human gliomas." (PMID 32856872, 2020). "The investigators employed WT1 in their diagnostic panel for glial neoplasms and astrogliosis and didn’t report a single false positive result." (PMID 32856872, 2020). "High-grade gliomas have a higher WT1 expression level compared with low-grade gliomas, and BCL2 is associated with the higher tumour grades, poorer patient survival, and the conferring of treatment resistance through its own action and the action of other gene family members." (PMID 24602166, 2014). "In turn, high levels of WT1 mRNA have been reported in gliomas at advanced clinical stages and with poor prognoses." (PMID 38499392, 2024). "Based on multivariate Cox regression analysis, the immune signature created using HOXC6, WT1, CD70, and OTP represented an independent prognostic factor for glioma patients with TERTp mutations." (PMID 38499392, 2024). "HOXC6, WT1, CD70, and OTP expression was upregulated in glioma tissues from patients with high-risk scores." (PMID 38499392, 2024). "EVs released from glioma cells, including Wilms tumor-1 (WT1), are taken up by microglia and downregulate the expression of thrombospondin-1, a negative regulator of angiogenesis." (PMID 38318528, 2024). "HOXC6, WT1, CD70, and OTP expression was elevated in glioma tissues from high-risk score patients carrying wild-type TERTp." (PMID 38499392, 2024). "We constructed a risk model using HOXA5, PTPN2, WT1, HOXD10, POSTN, ADAMDEC1 and MYBPH expression data from a cohort of patients in TCGA, and found that it had significant prognostic value for ATRX-wt glioma patients." (PMID 37812190, 2023). "In the test cohort, HOXA5, PTPN2, WT1, HOXD10, POSTN, ADAMDEC1 and MYBPH levels were elevated in glioma tissues with high-risk scores." (PMID 37812190, 2023). "Like survivin, WT1 protein is found to be greatly expressed in GBM compared with lower grade gliomas and studies have indicated its role in promoting tumorigenesis." (PMID 37046685, 2023). "Nevertheless, HOXA5, PTPN2, WT1, HOXD10, POSTN, ADAMDEC1 and MYBPH were overexpressed in ATRX-mt glioma tissues with high-risk scores compared with low-risk scores." (PMID 37812190, 2023). "Other than EGFRvIII and IDH1R132H, which are major players in glioma progression and prognosis, vaccines against survivin and WT1 protein have also been developed." (PMID 37046685, 2023). "In glioma tissues from the high-risk group of the training cohort, HOXA5, PTPN2, WT1, HOXD10, POSTN, ADAMDEC1 and MYBPH were highly expressed." (PMID 37812190, 2023). "In terms of tumor antigens used for pulse, glioma‐associated antigens (GAA) can be selected, such as WT1, TRP2, and IL‐13Rα2, or glioma‐specific antigen (GSA) EGFRvIII, while different antigen stimuli have discrepancy effects on DC function." (PMID 36464889, 2023). "In conclusion, a risk model constructed by 6 hypoxia-driven genes (WT1, HOXA2, HOXC6, MMP9, SHOX2 and MYOD1) provide valuable clinical utility for the prognostic prediction of glioma patients." (PMID 36118887, 2022). "The WT-1 protein is found secreted in glioma-derived EVs and downregulates thrombospondin-1 (Thbs1) in microglia, subsequently promoting angiogenesis which is vital in glioma progression." (PMID 36467419, 2022). "Among them, 22 genes had a degree score ≥10 and 6 genes (WT1, HOXA2, HOXC6, MMP9, SHOX2 and MYOD1) were selected to construct a signature to classify glioma patients into low- or high-risk groups." (PMID 36118887, 2022). "In another WT1 peptide vaccine trial among a group of 20 children with glioma, rhabdomyosarcoma, neuroblastoma, osteosarcoma, and clear cell sarcoma of the kidney, WT1-specific immune response was demonstrated in 4/18 (22%) evaluable patients." (PMID 34869013, 2021).
glioma (continued). "In a phase I trial, seven patients with high-grade gliomas were administered Wilms’ tumor 1 (WT1)-pulsed autologous DCs." (PMID 33767690, 2020). "In vitro and in vivo studies have confirmed the oncogenic role of WT1 in human gliomas including astrocytomas." (PMID 32856872, 2020). "The wild-type WT1 gene has been shown to be overexpressed in hematological malignancies and almost all solid tumors, while gliomas, as well as other solid tumors, have been found to express the WT1 protein." (PMID 30430205, 2019). "Accumulating evidence suggests that WT1 is also expressed in many different classes of intracranial tumors, including gliomas, oligodendrogliomas, ependymomas, and meningiomas and functions as an oncogene in these tumors." (PMID 29932419, 2018). "Previous studies in gliomas and breast tumors have also revealed, contrary to expectation, a high frequency of WT1 expressing samples with promoter (CpG island 188) hypermethylation." (PMID 24405639, 2014). "Our results are also consistent with another study in which the transcriptional target of PAX8, WT1, was decreased in low-grade compared with high-grade gliomas." (PMID 24602166, 2014). "Recently, CD97 was shown to be upregulated in three different GBM cell lines and to be one of the targets of the transcription factor WT-1 (Wilms tumor protein), the expression of which is also upregulated in gliomas." (PMID 24662753, 2014). "Because the WT1 gene is overexpressed in various types of tumors including glioma, a phase II clinical trial for a WT1 peptide vaccine was conducted for 21 patients with recurrent GBM." (PMID 23762610, 2013). "The highest ranked antigens included glioma antigens, WT1 and EGFRvIII, which are discussed in detail later in Section 7.3.2." (PMID 23762610, 2013). "HOXC6, WT1, CD70, and OTP were highly expressed in high-risk vs. low-risk glioma samples." (PMID 38499392, 2024). "Ideally, DCs pulsed with multiple common glioma antigens, such as WT1, EGFRvIII, and survivin, could serve as “off-the-shelf” therapies capable of treating a variety of GBM patients." (PMID 34041034, 2021). "DC vaccines primed with HLA class I-restricted WT1 peptides (WT1-DC) have been shown to be safe and feasible with few adverse reactions in patients with advanced cancers including lung, breast, stomach, biliary tract, pancreas, ovary, and high-grade glioma." (PMID 26690485, 2015). "In conclusion, an immune signature based on HOXC6, WT1, CD70, and OTP expression was shown to serve as an independent and specific prognostic indicator for patients with TERTp- mutant gliomas." (PMID 38499392, 2024). "Heatmap analysis showed that WT1, HOXA2, HOXC6, MMP9 and SHOX2 are highly expressed in high-hypoxia glioma tissues in the TCGA, whereas MYOD1 expression is reduced." (PMID 36118887, 2022). "Other glioma antigens that have been identified include IL13Ra2, EphA2, EphB6, AIM-2, HER-2, WT1, ARF4L, SART-3, SOX11, KIF1C, and KIF3C." (PMID 23762610, 2013). "In conclusion, our study revealed that an immune signature based on HOXA5, PTPN2, WT1, HOXD10, POSTN, ADAMDEC1 and MYBPH expression effectively predicted the prognosis of ATRX-wt glioma patients, and demonstrated that immunotherapy was effective for low-risk patients." (PMID 37812190, 2023). "A receiver operating characteristic curve analysis indicated that HOXA5, PTPN2, WT1, HOXD10, POSTN, ADAMDEC1 and MYBPH had significant prognostic value for the survival of ATRX-wt glioma patients (AUC = 0.84, 0.81, 0.79, 0.91, 0.80, 0.79 and 0.85, respectively)." (PMID 37812190, 2023).
glioma (continued). "A phase I trial in which patients with recurrent glioma received DCs pulsed with WT1 also reported no serious adverse events, and 6 of 10 patients showed a two-fold or greater increase in WT1-specific cytotoxic T lymphocytes by tetramer analysis." (PMID 34041034, 2021). "Fibroblast growth factor 4 (FGF4) also has been correlated with a greater malignancy profile in high-grade gliomas.The radioresistant cells had upregulated expression of many anti-apoptotic genes, including BCL2, CD74, and WT1, which regulates GBM cells proliferation and apoptosis." (PMID 30344926, 2018). "Because PAX8 binds to the promoter region of BCL2 and WT1 and enhances transcription, we investigated whether the downregulation of PAX8 would decrease the BCL2 and WT1 expression levels in glioma cells." (PMID 24602166, 2014). "Focusing on the TERTp-mutant glioma subtype, we developed an immune-related gene signature including HOXC6, WT1, CD70, and OTP that showed significant prognostic value for TERTp-mutant gliomas, but not for TERTp wild-type gliomas, in two TCGA cohorts." (PMID 38499392, 2024). "Similarly, we found that the expression of HOXC6, MMP9 and SHOX2 was higher in recurrent glioma tissues compared with primary glioma tissues and the expression of MYOD1 was decreased, while there were no significant changes in WT1 and HOXA2." (PMID 36118887, 2022).
Nephropathy (27 papers, 2015 to 2025). A nonspecific term referring to disease or damage of the kidneys. "Genetic analysis revealed two mutations that were likely associated with the patient’s nephropathy: a WT1 variant, c.388_389insAC (p.Pro130Hisfs*34), and an ACTN4 variant, c.2698T > A (p.Ser900Thr)." (PMID 40890712, 2025). "WT1 mutations located within the second to third zinc finger domains cause severe WT1-related nephropathy, clinically classified as a DDS subtype." (PMID 41450889, 2025). "Our suspicion was that nephropathy was likely due to secondary focal segmental glomerulosclerosis (FSGS) because both WT1 and ACTN4 mutations are more commonly associated with FSGS than diffuse mesangial sclerosis (DMS)." (PMID 40890712, 2025). "Disorders related to the WT1 pathogenic variants are lifelong, and glomerular damage along with an impaired filtration barrier can lead to nephropathy." (PMID 40332152, 2025). "Mutations of the Wilms tumor suppressor-1 gene (WT1) cause a WT1-related nephropathy characterized by a triad of glomerulopathy, defective genital development, and Wilms or gonadal tumor." (PMID 41450889, 2025). "We suspected that nephropathy was indicative of the progression of diffuse mesangial sclerosis or focal segmental glomerulosclerosis due to an underlying WT1 mutation and DDS." (PMID 40890712, 2025). "For the 11 cases diagnosed with WT1-related nephropathy, the decision to perform prophylactic nephrectomy was based on the genetic identification of WT1 mutations supporting the potential risk of malignancy." (PMID 39363361, 2024). "We analyzed the relationship between the genotype and clinical phenotype of WT1 mutation-related nephropathy in Chinese children." (PMID 37576146, 2023). "WT1 is expressed in podocytes throughout life and is critical for the functional integrity of the glomerular filtration barrier, therefore, nephropathy associated with WT1 mutations is dominated by podocyte damage." (PMID 37576146, 2023). "Future research should utilize a larger cohort with longer follow-up times and conduct comprehensive analyses to establish a scientific management plan for WT1 mutation-related nephropathy." (PMID 37576146, 2023). "The molecular and biological characteristics of WT1 mutation-related nephropathy determine the clinical type, pathological features, and renal survival time of the disease; and there was a strong correlation between the genotype and clinical phenotype." (PMID 37576146, 2023). "In this cohort the age of onset of nephropathy was 16.0 (9.0, 45.6) months, which was similar to the age of onset of WT1 mutation related nephropathy in Europe and the Middle East (Podonet Alliance) of 14.4 (3.6–51.6) months." (PMID 37576146, 2023). "This study aimed to analyze the clinical characteristics of nephropathy associated with WT1 gene mutations in Chinese children and explore the relationship between genotype and clinical phenotype." (PMID 37576146, 2023). "According to age stratification, the age of onset among children with WT1 mutation-associated nephropathy in China was most frequently between 3 months and 6 years of age (57/75, 76%)." (PMID 37576146, 2023). "A total of 75 cases of nephropathy associated with WT1 mutations in the study cohort met the inclusion and exclusion criteria." (PMID 37576146, 2023). "This study provides evidence for the diagnosis, treatment, prognostic assessment, and management of WT1 mutation-related nephropathy." (PMID 37576146, 2023). "Herein, we report 3 patients from 2 families with FS due to characteristic intron 9 WT1 mutations and unusual nephropathy of MPGN." (PMID 35211794, 2022). "Relatively little is known about phenotypic variability in nonsyndromic nephropathy associated with the gene encoding the WT1 transcription factor." (PMID 32843431, 2020). "The role of the heterozygous COL4A4 VUS variant in the cystic formation of WT1-related nephropathy kidney remains unclear." (PMID 41450889, 2025).